UBL7-DT (UBL7 divergent transcript)
Synonyms: UBL7-AS1
Gene: Long non-coding RNA gene on chromosome 15 (74,461,194 to 74,516,959, forward strand). Ensembl gene ENSG00000247240.
Gene Ontology:
Biological process: RNA processing
Cellular component: nucleolus